HIF1A (hypoxia inducible factor 1 subunit alpha)
Diseases named in the same sentence as HIF1A in open-access papers (continued):
Sharing a sentence is not in itself a finding about the gene and the disease.
bladder cancer (continued). "The present study has been the first to indicate that upregulation of MT3 by hypoxia in human bladder carcinoma cells is dependent on HIF-1α and HIF-2α, which are well-known to be overexpressed in bladder cancer in vivo." (PMID 30813460, 2019). "In human bladder cancer cells (T24), magnolol decreases the production of H2O2 and the expression of HIF-1α and increases the degradation of HIF-1α." (PMID 31240205, 2019). "In bladder cancer cell lines, LMWF (Sargassum hemiphyllum) inhibited angiogenesis through interaction with the HIF-1a/VEGF signaling pathway." (PMID 30621045, 2019). "In conclusion, we demonstrated that AE-AS exhibits a potent antiangiogenic activity in bladder cancer through suppressing WSB-1-induced pVHL degradation, HIF-1α induction/activity, and angiogenesis-related signaling pathways." (PMID 28710377, 2017). "Hif-1α specifically binds two HREs in the UCA1 lncRNA promoter, leading to its activation in hypoxic bladder cancer cells." (PMID 28327666, 2017). "Our data showed that knocking down WSB-1 with si-WSB-1 markedly reversed the elevation of nuclear HIF-1α level and VEGF synthesis in hypoxic T24 cells, indicating that WSB-1 plays a crucial role in the activation of HIF-1α/VEGF cascade in bladder cancer." (PMID 28710377, 2017). "HO-1 expression was upregulated together with HIF-1α, HIF-2α, and Nrf2 in bladder cancer in comparison to healthy tissue." (PMID 26927195, 2016). "Recently, HIF-1α activation and subsequent PGK1 up-regulation has also been demonstrated in bladder cancer." (PMID 26468005, 2015). "Herein, we report that in the bladder cancer T24 cells, prolonged exposure to hypoxia induces the elevation of HAF, resulting in the switch of HIF-1α to HIF-2α, the process of which is mediated by NF-κB pathway." (PMID 24316875, 2014). "The results allow us to formulate a preliminary hypothesis that HIF-1α, ANG-2, and IL-1β may be biomarkers characteristic of bladder cancer, having elevated concentrations in patients with that disease." (PMID 39275392, 2024). "Stabilization of HIF-1α increases FGFR3 mRNA and protein levels in bladder cancer." (PMID 38542288, 2024). "For example, sulforaphane, a natural agent abundant in cruciferous vegetables, has been demonstrated to suppress the proliferation of non-muscle invasive bladder cancer cells via blocking HIF-1α-mediated glycolysis in hypoxia." (PMID 35293283, 2022). "Moreover, suppression of the HIF-1α/BNIP3/Beclin-1 signaling pathway inhibited autophagy and enhanced both gemcitabine-induced apoptosis and gemcitabine sensitivity in bladder cancer cells under hypoxic conditions." (PMID 36551540, 2022). "A series of previous studies have demonstrated that HIF-1α can exacerbate bladder cancer progression, including promoting EMT process and cell growth and conferring the chemo-resistance to cisplatin of bladder cancer cells." (PMID 35293283, 2022). "In this study, we aimed to establish the metabolic signal axis: PI3K/AKT/HIF-1α dependent glycolysis promotion, metabolic stress, AMPK activation and mTORC1 suppression, which induces autophagic cell death in bladder cancer cells and reveals the exact anticancer mechanism of Vitamin K2." (PMID 32382009, 2020). "Indeed, our present results revealed that CDDP treatment increases HIF-1α protein level, its recruitment onto the putative HIF-1α-binding site of miR-424 and enhances its transcriptional activity in bladder cancer cells under normoxia." (PMID 32522234, 2020). "Additionally, AE-AS, z-ligustilide, and n-butylidenephthalide have a similar activity on the inhibition of HIF-1α and VEGF expression in various bladder cancer cell lines, such as T24, HT1376, and HT1197." (PMID 28710377, 2017). "In the second part of the study, an HIF-1α inhibitor YC-1 was added and we found that a decrease in the HIF-1α expression resulted in a decrease in VEGF expression and an increase in the permeability of bladder cancer cells during hypoxia." (PMID 29267502, 2017).
bladder cancer (continued). "Taken together, Foxp3 can be detected to be able to bind with HIF-1α protein, particularly upon hypoxia or MG132 treatment and enahnce HIF-1α protein expression through decreasing ubiquitin-mediated proteasomal degradation in human bladder cancer cells." (PMID 27557492, 2016). "The expression of HO-1 has not so far been examined in relation to Nrf2, HIF-1α, and potential mediators of angiogenesis in human bladder cancer." (PMID 26927195, 2016). "MiR-155 was shown to target HIF-1α in murine and human cells; therefore, its downregulation may be responsible for the upregulation of HIF-1α observed here in bladder cancer cells." (PMID 26927195, 2016). "Similarly, factors regulated by hypoxia (HIF-1α and HIF-2α) and their target VEGF were upregulated in bladder cancer samples." (PMID 26927195, 2016). "Another study investigated on the function of UCA1 in hypoxic bladder cancer, revealing that UCA1 could function as a HIF-1α-targeted lncRNA to enhance bladder cancer cell invasion." (PMID 27517147, 2016). "The metaanalysis from 2 larger published datasets of bladder cancer showed Foxp3 expression is significantly associated with GLUT−4, −9 and VEGF-A, -B, -D mRNA expression, rather than HIF-1α mRNA expression." (PMID 27557492, 2016). "Moreover, suppression of PI3K/AKT and HIF-1α attenuated Vitamin K2-increased glucose consumption and lactate generation, indicating that Vitamin K2 promotes PI3K/AKT and HIF-1α-mediated glycolysis in bladder cancer cells." (PMID 32382009, 2020). "In the present study we demonstrated that the Foxp3 can enhance HIF-1α protein expression through decreasing ubiquitin-mediated proteasomal degradation in bladder cancer cells and influences VEGF signaling and intratumoral immunity, contributing an unfavorable prognosis in bladder cancer." (PMID 27557492, 2016). "Importantly, HIF–1α was revealed to induce CD24 mRNA expression by binding to the CD24 promoter in prostate and bladder cancer cells under hypoxia, identifying CD24 as a transcriptional target of HIF–1α and a critical downstream effector of HIF–1α–mediated survival and metastasis." (PMID 26444008, 2015). "Having determined variability in the expression of proline-hydroxylated HIF-1α in VHL competent cell lines, we used a panel of tissue microarrays to evaluate the expression of total and proline-hydroxylated HIF-1α in hypoxic head and neck, breast, lung and bladder carcinomas." (PMID 24563687, 2014). "In addition, the expression of ZEB1 and HIF-1α were significantly increased in high-grade, invasive, and metastatic bladder cancer tissues as compared to the low-grade, superficial, and non-metastatic bladder cancer tissues." (PMID 37627900, 2023). "Abnormal activation of HIF-1A and related metabolic target genes in the M2 subtype not only indicates a response to hypoxia-induced therapy but could also be used as a prognostic biomarker for bladder cancer patients." (PMID 33985530, 2021). "Additionally, HIF-1α and HIF-2α are upregulated at the mRNA level in urothelial bladder cancer and correlate with elevated VEGF expression in tumors and with its increased concentration in the plasma of patients affected by bladder cancer in comparison to healthy controls." (PMID 26927195, 2016). "Our earlier studies indicated that sulforaphane decreased glycolytic metabolism in a hypoxia microenvironment by inhibiting hypoxia-induced HIF-1α and HIF-1α trans-localization in non-muscle-invasive bladder cancer cell lines." (PMID 35563563, 2022). "Previously, we showed that necrosis, HIF-1α and CA9 but not Glut-1 or a 26-gene head and neck signature predicted benefit from the addition of CON to RT in patients with bladder cancer." (PMID 27441495, 2016). "Therefore, it is suggestive that HIF-1α/miR-424/UNC5B/SIRT4 regulatory axis contributes to the acquisition and/or the maintenance of CDDP resistance of bladder cancer cells irrespective of hypoxia." (PMID 32522234, 2020).
bladder cancer (continued). "Under our experimental conditions, HIF-1α-target gene CA9 but not HIF-1α-unrelated RPL13A was induced in T24 cells following CDDP exposure, indicating that CDDP enhances the expression and the transcriptional activity of HIF-1α in bladder cancer cells." (PMID 32522234, 2020).
atherosclerosis (106 papers, 2010 to 2026). A disease characterized by the build-up of fatty material and calcium deposition in the arterial wall resulting in partial or complete occlusion of the arterial lumen. "Further investigation is required to fully understand the specific mechanisms underlying the dual effects of HIF-1α and their implications for the progression of atherosclerosis." (PMID 40376262, 2024). "They showed that the additional deletion of HIF-1α in myeloid cells from ApoE-deficient mice reduced atherosclerosis and NC formation by limiting macrophage necroptosis." (PMID 38576612, 2024). "Key molecular pathways include activation of the sympathetic nervous system and downstream signaling processes such as those mediated by HIF-1α, which have been implicated in the development of hypertension and atherosclerosis." (PMID 38672697, 2024). "Lox-1 upregulation, endothelial and vascular inflammation caused by HIF-1α exacerbate foam cell formation and atherosclerosis." (PMID 36724056, 2023). "It has been found that atherosclerotic lesion formation is associated with an upregulated expression of HIF-1α in atherosclerotic lesions and antigen-presenting cells (APCs) in atherosclerosis-prone mice." (PMID 37981648, 2023). "In oxidized low-density lipoprotein-stimulated endothelial cells, upregulation of miR-19a is induced by hypoxia-inducible factor (HIF)-1α and is associated with vascular inflammation and atherosclerosis progression." (PMID 35329950, 2022). "Conversely, bone marrow transplantation from mice presenting a constitutive activation of HIF-1α (mice deficient for Von Hippel–Lindau tumor suppressor) increased atherosclerosis." (PMID 35386720, 2022). "Recently, Karshovska and associates documented that a high level of HIF-1α regulation impairs the mitochondrial bioenergetic and elevates macrophage necroptosis in the atherosclerosis." (PMID 35205167, 2022). "HIF-1α expression was significantly stronger in patients with CAD than controls, and the level of HIF-1α was associated with the severity of atherosclerosis and a higher level of coronary collaterals." (PMID 33438846, 2021). "In this review, we have provided an overview of the functional role of cellular senescence and HIF-1α implications for vascular functions in advanced age and/or aging-associated diseases, with a particular focus on atherosclerosis." (PMID 31941032, 2020). "While we were preparing this manuscript, a study reported pathogenic actions of CD163+ macrophages in atherosclerosis where these cells showed activation of HIF1α and VEGF expression and increased vascular permeability and inflammatory cell recruitment." (PMID 30092836, 2018). "We discovered a previously uncharacterized role for HIF-1α in metabolic reprogramming and activation of vascular endothelium under disturbed flow, which simulates hemodynamics associated with atherosclerosis." (PMID 28556776, 2017). "HIF-1α has been implicated in the pathogenesis of atherosclerosis, AAA formation and pulmonary hypertension." (PMID 27363580, 2016). "Hypoxia inducible factor-1α (HIF-1α) pathway is associated with many vascular diseases, including atherosclerosis, arterial aneurysms, pulmonary hypertension and chronic venous diseases." (PMID 27363580, 2016). "Furthermore, the progression of atherosclerosis has been linked to the dysregulation of miR-107, which resulted in the increased expression of MiD51 by targeting hypoxia-inducible factor-1α (HIF-1α)." (PMID 38203413, 2023). "HIF-1α is an important transcriptional factor associated with angiogenesis, aerobic glycolysis, and pro-inflammatory processes, which are also confirmed to be risk factors for atherosclerosis." (PMID 38203413, 2023).
atherosclerosis (continued). "Similarly, myeloid-resident HIF1α has been implicated in vascular inflammation and angiogenesis with impacts on atherosclerosis, femoral arterial injury and hindlimb ischemia." (PMID 37344842, 2023). "Thus, both HIF1α and HIF2α accumulate during atherosclerosis, and increases in HIF abundance are associated with the progression from early to late-stage lesions." (PMID 34290616, 2021). "Hence, a causal role of HIF-1α in macrophages for the pathogenesis of atherosclerosis remains elusive at this time." (PMID 27034586, 2016). "Our in vitro and in vivo results suggest spatial inhibition of glycolytic metabolism and HIF-1α signaling may be a suitable approach for future arterial wall-based therapies that target disturbed flow-activated endothelium associated with focal atherosclerosis." (PMID 28556776, 2017). "Furthermore, Hif1α has been implicated in the pathogenesis of atherosclerosis." (PMID 25333702, 2014). "Endothelial HIF-1α promotes atherosclerosis by triggering miR-19a mediated CXCL1 expression and monocyte adhesion." (PMID 40478326, 2025). "Similar studies in cardiovascular medicine shown that atherosclerosis angiogenesis was mediated by HIF-1α signaling pathway." (PMID 39891057, 2025). "For example, specific knockdown of HIF-1α in adipocytes can ameliorate the pathological process of atherosclerosis by inhibiting the production of ceramides." (PMID 40143173, 2025). "In this study, EGFR, VEGFA, HSP90AA1, SRC, HIF1A, CXCR4 and IGF1R were identified as key hub targets, which linked anthocyanins with atherosclerosis." (PMID 40478326, 2025). "The lncRNA AC078850.1 mediates cellular pyroptosis in atherosclerosis by increasing HIF‐1α‐mediated transcription of the ITGB2 gene." (PMID 40032652, 2025). "In mice, deletion of HIF-1α in macrophages or adipocytes inhibited the occurrence of atherosclerosis, supporting a pathogenetic role of HIF-1α in atherosclerosis." (PMID 40376262, 2024). "CIH stimulates the upregulation of the hypoxia-inducible transcription factor HIF1A, contributing to the independent risk of OSA for atherosclerosis and heightened cardiovascular mortality." (PMID 38443855, 2024). "The role of HIF-1α in atherosclerosis is complicated as both detrimental and protective effects have been reported." (PMID 40376262, 2024). "For example, the presence of pro-inflammatory and hypoxic states, a common feature in atherosclerosis, is well known to upregulate the hypoxia-inducible factor 1 subunit alfa (HIF-1α) in endothelial cells." (PMID 39259392, 2024). "In this study we have utilized ApoE knockout mice to initially study the role of HIF-1α in myeloid cells in atherosclerosis." (PMID 39473019, 2024). "The siMiD49, siMiD51 and miR-107 mimic regressed experimental atherosclerosis, as did the treatment with the miR-107 mimic, which reduced the expression of MiD51 and HIF-1α proteins." (PMID 38203413, 2023). "In this study, we first screened atherosclerosis-associated lncRNA AC078850.1 and predicted its proatherogenic functions via its interaction with the RNA binding protein HIF-1α, using multiple bioinformatics." (PMID 37371830, 2023). "This novel lncRNA AC078850.1/HIF-1α complex was required to advance our understanding of atherosclerosis and provide potential therapeutic agents against it." (PMID 37371830, 2023). "Taken together, we demonstrated the potential roles of lncRNA AC078850.1/HIF-1α complex in atherosclerosis, which provided an important opportunity to advance the understanding of atherosclerosis." (PMID 37371830, 2023). "Hypoxia and HIF1A have been recognized to be important contributors to progression of atherosclerosis, as they can participate to endothelial dysfunction and stimulate inflammatory and angiogenic responses within the lesion." (PMID 37748649, 2023).